BRCA1 (BRCA1 DNA repair associated)
Diseases named in the same sentence as BRCA1 in open-access papers (continued):
Sharing a sentence is not in itself a finding about the gene and the disease.
tumor (continued). "Strikingly, cell death was reduced in Fancc− cells by additional deletion of the BRCA1 tumor suppressor, resulting in elevated clonogenic survival." (PMID 26324327, 2015). "Although the three levels of BRCA1 tumoral expression were correlated inside the same tumor, highly heterogenous intra-tumoral expression was observed, hampering accurate quantification." (PMID 26490435, 2015). "Since its discovery, researchers have intensively investigated the mechanisms by which full-length BRCA1 (p220) functions as a tumor suppressor." (PMID 25699710, 2015). "The authors propose that tumor suppressor functions of BRCA1 primarily stem from its role as a regulator of heterochromatin." (PMID 26136771, 2015). "• M′′ - those with lower co-expression in normal vis-a-vis PDAC, or lower co-expression in BRCA1 tumours vis-a-vis BRCA2 tumours." (PMID 25521701, 2014). "There was a positive correlation between plasma and tumor mRNA levels of BRCA1 (rho = 0.696, P < 0.001) and TS (rho = 0.620, P < 0.001, Spearman rank correlation test)." (PMID 25496700, 2014). "Expression of BRCA1 was observed in 61 cases (43.88%) and was related to tumor size (T stage) (p=0.001), and gender (p=0.017)." (PMID 25594033, 2014). "Despite evidence that maintenance of genome integrity by BRCA1 serves as an important tumor suppressor activity, the exact biochemical activity that responsible for tumor suppression by BRCA1 still remains elusive." (PMID 24704793, 2014). "The authors also observed that levels of ErbB2, pErbB2, and cyclin D1 increased in a time-dependent manner in the mammary glands in BRCA1-deficient mice, and CDDO-Me inhibited the constitutive phosphorylation of ErbB2 in tumor tissues from these mice." (PMID 24552536, 2014). "This is consistent with earlier findings that ER-negative tumours (BRCA1 tumours) display aberrant expression of NFκB which makes these tumours highly aggressive." (PMID 25521701, 2014). "Metastatic tumors stained more intensely for BRCA1 (82.3% strong staining) compared to primary tumor sites (71.4% strong staining; p = 0.041)." (PMID 24904527, 2014). "The expression of replication factor C complex (RFC2, RFC3 and RFC4) is indicative of proliferative potential (high cell division rates) of BRCA1 tumours." (PMID 25521701, 2014). "We found variants in the five genes APC, BRCA1, RET, RNASEL, and STK11 that were linked to autosomal dominant forms of cancer or neoplasm as well as four complex risk variants in ELAC2, MSR1, AIP, and SDHB." (PMID 25333069, 2014). "BRCA1 has been shown to regulate de novo fatty acid synthesis, and protect tumor cells against oxidative stress." (PMID 25010005, 2014). "BRCA1 tumours displayed higher co-expression compared to BRCA2 tumours, ∼15700 PPIs with higher correlations." (PMID 25521701, 2014). "FANCJ (originally named BRCA1 interacting C-terminal helicase (BACH1) or BRCA1 interacting helicase (BRIP1) was first discovered by its physical interaction with BRCA1, a known tumor suppressor and mediator of double strand break (DSB) repair." (PMID 25374583, 2014). "Tumor and genomic DNA from patients with BRCA1 promoter methylation were screened for the three key founder mutations in the Ashkenazi Jewish population: BRCA1 185delAG, 5382insC, and BRCA2 6174delT." (PMID 25136623, 2014). "The cooperation between BRCA1 and vitamin D3 is maintained and even exaggerated in mammosphere cultures, which are enriched with stem-like, tumor initiating mammary cells." (PMID 25460500, 2014). "One of the reasons that this was obscured in univariate analysis is that the BRCA1-likeCGH tumors ended up in the non- BRCA2-likeCGH tumor group, thereby confounding the analysis." (PMID 24887359, 2014).
tumor (continued). "Six samples were found to be positive for methylation of the BRCA1 promoter, counting three basal-like non-BRCA1/2 tumors, one normal-like non-BRCA1/2 tumor, one basal-like sporadic tumor and one lumB sporadic tumor." (PMID 24479546, 2014). "There were significant correlations between plasma and tumor mRNA levels of BRCA1 (rho = 0.696, P < 0.001) and TS (rho = 0.620, P < 0.001)." (PMID 25496700, 2014). "BRCA1 is a tumor suppressor that undergoes active nuclear import and export, which can provide a regulatory function." (PMID 23873416, 2014). "Future studies of BRCA1 modifications by oxidative stress are likely to help our understanding of BRCA1 function in the oxidative stress response and tumor suppression." (PMID 24704793, 2014). "We found a relationship between BRCA1 expression and tumor size, with tumor size been grouped as T stage between I/II and III/IV, for statistical purposes (p=0.001), and with gender (p=0.017)." (PMID 25594033, 2014). "Out of the 22 BRCA1 methylated positive cases, only 19 archived tumor tissues were available for BRCA1 methylation analysis." (PMID 25403427, 2014). "Tumor grades of non-BRCA1/2 tumors were distributed more evenly, but compared to sporadic tumors, overall slightly higher." (PMID 24479546, 2014). "In this study we found wild type BRCA1/1a proteins to induce expression of caveolin-1, a tumor suppressor in BRCA1-mutant serous epithelial ovarian cancer (SEOC) cells by immunofluorescence analysis." (PMID 25594072, 2014). "Overall, we noticed considerable drop in co-expression for PDAC vis-a-vis normal, whereas BRCA1 tumours showed higher co-expression vis-a-vis BRCA2 tumours." (PMID 25521701, 2014). "The significance of these regulations in the tumor suppressor function of BRCA1 remains to be determined." (PMID 24704793, 2014). "Established elements of BRCA1 function were analysed in freshly isolated, morphologically non-neoplastic, primary HMECs and skin fibroblasts derived from multiple BRCA1+/+ and BRCA1mut/+ tumour-free women." (PMID 25400221, 2014). "Of six tumour suppressor genes investigated BRCA1, BRCA2, and p14 appeared to be under strong epigenetic silencing." (PMID 24607238, 2014). "To test how Aur A/B and BRCA1/2 affect tumor growth, we injected Capan-1 and OVCA433 cells expressing various shRNAs along with their control cells into nude mice and analyzed the tumor growth." (PMID 24775809, 2014). "Most recently, two separate groups demonstrated the importance of two domains, BRCT and RING, in the tumor suppressor function of Brca1 in mouse models." (PMID 24704793, 2014). "Specifically, Hsu and White had validated that the BRCA1 tumour suppressor can form a link with γ-tubulin, a critical protein within the centrosome." (PMID 25548681, 2014). "The convergence of IGF1R-mediated cell survival pathways and BRCA1-mediated tumor protective pathways is of major basic and clinical relevance." (PMID 24904527, 2014). "Normal tissue DNA was not available for one TNBC patient carrying a deletion of one exon in BRCA1 in their tumor sample." (PMID 25475740, 2014). "The E3 ligase activity of the BRCA1:BARD1 heterodimer is believed to be implicated in tumor suppression, as missense mutations in the RING domain of BRCA1 that disrupt the interaction with E2 have been reported in patients." (PMID 24695549, 2014). "A similar analysis in BRCA1 vs BRCA2 tumours highlighted increase in PPI co-expression around the mitotic regulators CDK1, CDC20 and CKS1B and the histone deacetylases HDAC1 and HDAC6; these are known drug targets for which inhibitors have been developed." (PMID 25521701, 2014). "The results indicated that RRM1 expression levels between peripheral blood and tumor tissue were linearly correlated (R2 = 0.045, P = 0.048) and similar linear correlations were observed for BRCA1 expression (R2 = 0.021, P < 0.001)." (PMID 24591771, 2014).
tumor (continued). "Here we show for the first time that the BRCA1-3’UTR-variant predicts Stage IV disease, likely due to aggressive tumor biology." (PMID 24915755, 2014). "In view of this established data, it was reasonable to postulate that if Tax and BRCA1 were acting within the same host cells, the potent Tax tumorigenic activities would likely antagonize BRCA1expression and its various tumor suppressing actions." (PMID 24586743, 2014). "We analyzed the ROC curves for all previously known potential factors, including age, tumor size, hemoglobin, along with our potential markers: BRCA1, BRCA2, RAD51, FANCD2, BLM and BRIP1." (PMID 24708616, 2014). "BRCA1 is a multifunctional tumor suppressor, whose expression is activated by the estrogen (E2)-liganded ERα receptor and regulated by certain recruited transcriptional co-activators." (PMID 24586743, 2014). "The exact role of the E3 ligase activity of BRCA1 in tumor suppression still remains the subject of debate." (PMID 24704793, 2014). "BRCA1 levels in plasma and tumor were higher in the docetaxel-sensitive than in the docetaxel -resistant group." (PMID 25496700, 2014). "The knockdown of Aur A or Aur B in Capan-1 cells inhibited the tumor growth, but the silencing of BRCA1 alone promoted the tumor growth in mice, compared with relative control cells." (PMID 24775809, 2014). "BRCA1 and BRCA2 are tumor suppressor genes encoding proteins involved in a common pathway of DNA double-strand repair." (PMID 24959366, 2014). "Tumor with high expression of BRCA1 is 800-to-more than 1000-fold sensitive to docetaxel, but 10-1000-fold resistant to cisplatin." (PMID 25496700, 2014). "The Spearman rank correlation test showed a correlation between plasma and tumor mRNA levels of BRCA1 (rho = 0.647, P < 0.001) and between plasma and tumor levels of TS (rho = 0.615, P < 0.001) (available online)." (PMID 25496700, 2014). "The role of BRCA1 protein as a tumour suppressor became even more evident with its role in the intensification of the centrosome and at the G2/M checkpoints of the cell cycle." (PMID 25548681, 2014). "BRCA1- and BRCA2-associated tumours showed few tandem duplications, indicating that the mechanisms responsible for chromosomal rearrangements in these tumours were distinct from those in triple-negative tumours, which exhibited tandem duplications." (PMID 24792170, 2014). "Top enriched terms in KEGG pathways and Biological Process in disrupted complexes in pancreatic (normal vs PDAC) and breast (BRCA1 vs BRCA2) tumours (using DAVID)." (PMID 25521701, 2014). "It is well known that the activation of Aurora A/B (Aur A/B) or inactivation of BRCA1/2 induces tumor formation." (PMID 24775809, 2014). "While most complexes showed a decrease in co-expression from normal to PDAC (159 out of 256) and from BRCA1 to BRCA2 tumours (225 out of 277), interestingly a considerable number of complexes showed an increase (96 and 52)." (PMID 25521701, 2014). "FANCJ likely operates with other downstream BRCA-FA proteins, such as BRCA1, and related factors also classified as tumor suppressors to facilitate recombinational repair (potentially following unhooking of the processed cross-link)." (PMID 25374583, 2014).
tumor (continued). "Through correlation analysis of RRM1, ERCC1, and BRCA1 mRNA expression levels, our results indicated a linear correlation between peripheral blood and tumor tissue RRM1 expression." (PMID 24591771, 2014). "In contrast, minimal drug treatment effects were observed in the Brca1-wild type tumor model indicating an overall concordance of histopathological and tumor volume changes following drug treatment." (PMID 24748377, 2014). "BRCA1 levels in plasma (docetaxel-sensitive: 1.25; docetaxel-resistant: 0.50, P < 0.001) and tumor (docetaxel-sensitive: 8.81; docetaxel-resistant: 4.88, P < 0.001) were positively associated with docetaxel sensitivity." (PMID 25496700, 2014). "In the case of BRCA1 vs BRCA2 tumours, only four of the influential TFs (GATA3, ESR1, FOXA1 and XBP1) were identified as differentially expressed." (PMID 25521701, 2014). "BAP1 (BRCA1-Associated Protein 1) was initially identified as a protein that binds to BRCA1 and is now recognized as a tumor suppressor that mediates its effects through chromatin modulation, ubiquitin-proteasome system and the DNA damage response pathway." (PMID 25536104, 2014). "Knock-in mice with deficient BRCA1 RING finger mutant display diverse genomic instability and tumor-forming phenotypes." (PMID 25426449, 2014). "As already suggested in other studies, BRCA1 mutation was also correlated with high level of phosphorylated form of AKT in several other cell lines and tumour models." (PMID 25010005, 2014). "Only 3 of the 14 TN tumours with BRCA1 promoter hypermethylation presented high 53BP1 protein levels." (PMID 24191908, 2013). "It was also proposed that BRCA1 functions, including tumor suppression, can be explained by the ability of BRCA1 to ubiq-uitinate the histone H2A within satellite DNA, thus maintaining heterochromatin in a transcriptionally silenced state." (PMID 23802008, 2013). "Given its role as a tumour suppressor and its stimulated nucleo-cytoplasmic shuttling properties after DNA damage, it is possible that in response to DNA damaging agents, BRCA1 preferentially regulates the translation of genes involved in DNA repair." (PMID 23805307, 2013). "Consistently, BRCA1 complexed with BARD1 has tumor suppression properties and is involved on protein ubiquitination for degradation." (PMID 23408952, 2013). "Most tumor suppressors promote autophagy, which has been suggested as a potential mechanisms to inhibit tumor development, and only few of them, such as BRCA1, produce the opposite effect." (PMID 24349488, 2013). "The function of BRCA1 protein in tumorigenesis has been found to be complex, and as a tumor suppressor, it is postulated that reduced expression leads to multiple abnormalities, including a defect in the homologous recombination (HR) pathway of DNA repair." (PMID 23855721, 2013). "The authors' conclusion that most BRCA1 tumor suppressor functions are due to its role in the maintenance of heterochromatin structure is inconsistent with the idea that the BRCA1 ubiquitin ligase function is dispensable for tumor suppression." (PMID 23802008, 2013). "We found less BRCA1 nuclear staining in the tumor tissue of frozen tissue specimens and in contiguous FFPE tissue with higher histological grade." (PMID 23855721, 2013).
tumor (continued). "Notably, in vitro studies propose that activation of the PIK3CA/mTOR pathway may be important in tumours with deficient homologous recombination, suggesting a possible role in gaining resistance to poly ADP ribose polymerase (PARP) inhibitors in BRCA1/2 deficient tumours." (PMID 23971979, 2013). "BRCA1 promoter hypermethylation was detected in 18 tumours and was significantly associated with the TN status." (PMID 24191908, 2013). "Proliferation of cucurbitacin B treated parental cells and scrambled cells harboring the functional (wt) BRCA1 tumor suppressor was mildly reduced when compared to its paired untreated control cells." (PMID 23393598, 2013). "Sensitization to radiation and alkylating agents was enhanced in DSB repair-deficient cells, consistent with the remarkable sensitivity to PARP inhibition of BRCA-1 and BRCA-2-deficient tumor cells." (PMID 23565244, 2013). "Recently, proteomic analysis revealed the binding of ABRAXAS to the BRCA1 BRCT (BRCA1 carboxyl-terminal) repeats, which are essential elements in tumour suppression." (PMID 23586058, 2013). "BRCA1 combines with other tumor suppressors, DNA damage sensors, and signal transducers to form a large multisubunit protein complex known as the BRCA1-associated genome surveillance complex (BASC)." (PMID 24312913, 2013). "It has been recently published that reduced BRCA1 expression correlates with a better outcome following platinum chemotherapy, and clinical trials report on significant anti-tumour activity following PARP inhibitor treatment in BRCA1-deficient patients." (PMID 23301673, 2013). "We also assessed germline and somatic genomic imbalances in 15 patients (blood and tumor matched samples), 7 of which carried BRCA1/2 germline mutations (3 in BRCA1 and 4 in BRCA2), and 6 and 2 of which harbored BRCA1/2 wild type and BRCA1/2 UVs, respectively." (PMID 23469205, 2013). "Gene ontology analysis revealed that the most enriched function of the genes that are translationally regulated is cellular maintenance, which is considered today as the major role of BRCA1 contributing to its tumour suppressor activity." (PMID 23805307, 2013). "BRCA1 is a tumor suppressor gene involved in the control of cell cycle progression and of DNA double strand break (DSB) repair." (PMID 23374397, 2013). "Similar to BRCA1/2-defective tumor cells, PTEN-null PCa cells have been reported to be sensitive to PARPi." (PMID 23565244, 2013). "We show that control of Notch signalling is an important aspect of BRCA1 tumour suppression with roles in the differentiation, basal-luminal lineage specification and growth control of breast tissue." (PMID 23863842, 2013). "Mutations in BRCA1 and BRCA2 genes confer high lifetime risks of breast and ovarian cancer, among other neoplasias." (PMID 23613828, 2013). "An increased therapeutic ratio can be accomplished by either tumor-specific sensitization (BRCA1 nuclear export and HR attenuation) or by neuron-specific radioprotection (GSK3β inhibition and NHEJ potentiation)." (PMID 23388100, 2013). "Alvarez and colleagues found that part of the BRCAX tumours showed aCGH profiles similar to those of BRCA1 tumours." (PMID 23383274, 2013). "The investigators concluded that the ubiquitin ligase function of BRCA1 was dispensable for tumor suppression, while the recognition of phosphoproteins by the BRCT domains of BRCA1 was essential for suppression of tumor formation." (PMID 23802008, 2013).